MDM2 (MDM2 proto-oncogene)
Diseases named in the same sentence as MDM2 in open-access papers (continued):
Sharing a sentence is not in itself a finding about the gene and the disease.
cancer (continued). "MDM2 is a ubiquitin E3 ligase, frequently overexpressed in human cancers." (PMID 35625571, 2022). "In addition, our results indicated that the growth inhibitory effect of S9 is more apparent in MDM2-overexpressed cancer cells." (PMID 36071402, 2022). "This inspired us to search for novel MDM2 inhibitors that could abrogate MDM2 E3 ligase activity and downregulate the activity of MDM2-MDMX in cancer cells." (PMID 35625571, 2022). "Hinokiflavone could work as a potential anti-cancer therapeutic agent in malignancies with MDM2 overexpression." (PMID 35625571, 2022). "Since MDM2 inhibitors are now being under extensive investigation for the treatment of cancer by recent research works, application of those drugs for the treatment of cardiovascular disease may be anticipated." (PMID 35628577, 2022). "This indicates that dual MDMX/MDM2 inhibitors may be more suitable in cancers that have high levels of MDMX." (PMID 36678521, 2022). "Besides, MDM2 proto‐oncogene (MDM2) inhibitor enhanced the antipancreatic cancer effects of USP22 overexpression." (PMID 34743406, 2022). "In addition to the role that MDM2 plays in cancer regulation, it has also been shown to ubiquitinate Lys47 of HDAC1 in vascular calcification." (PMID 34577077, 2021). "The overall MDM2 gene amplification frequency in human cancer varies between 3.5 and 4.4%." (PMID 33799733, 2021). "Interestingly, four of the six targetable genes, CDK4, RAD50, CHEK1, and MDM2, were involved in two or more major cancer-related pathways." (PMID 33557149, 2021). "MDM2 gene is a proto-oncogene, and its expression mediates important cancer pathology." (PMID 35126089, 2021). "MDM2 antagonists such as Nutlin and its derivatives are being developed as cancer therapeutics." (PMID 34532654, 2021). "In order to target specific E3 ligases for cancer drugs development, the RING type MDM2 (murine double minute 2) could be the first choice due to its overexpression in various human cancers." (PMID 35006464, 2021).
cancer (continued). "MDM2 and LRP1B have recently been reported as mutational cancer drivers." (PMID 34313788, 2021). "Furthermore, the existence of many MDM2 binding partners, and the reported synergy between MDM2 antagonists and (targeted) therapy, both in GCTs and other cancers, make this an interesting and relevant target as well." (PMID 34769213, 2021). "CDKN2A SCND leads to inactivation of both P16INK4a and P14ARF (two endogenous inhibitors for CDK4 and MDM2) in >90% CDKN2A-deleted cancers, it needs to study whether CDK4 and MDM2 inhibitor drugs could be used to prevent hematogenous metastasis of cancers." (PMID 35004325, 2021). "In contrast, the upregulation in XIAP expression observed in cancer cells in response to DNA damage is associated with two proteins: Che-1 protein mediates activation of XIAP NF-κB-dependent transcription, while Mdm2 mediates XIAP by IRES-dependent translation." (PMID 34445588, 2021). "Moreover, in addition to RAGE, other repair factors such as BRCA1, RAD51 and Mdm2 are known to express their multiple splice variants in SCLC and other cancers." (PMID 34200336, 2021). "Amplification of MDM2 or MDM4 genes in some cancers results in decreased patient survival." (PMID 34572735, 2021). "Herein, (+)-strebloside and digoxin and their aglycones were all found to bind to MDM2, indicating that these cardenolides could be a new type of MDM2 inhibitor to show some therapeutic potential for the treatment of cancer." (PMID 34577146, 2021). "Therefore, the targeted delivery of MDM2 inhibitors is crucial to induce targeted apoptosis of cancer cells and limit toxicity in normal tissues." (PMID 34307171, 2021). "Multiple studies revealed that MDM2 is deeply involved in cancer development and progression." (PMID 34572735, 2021).
cancer (continued). "In many cancers, MDM2 amplification or altered protein expression can be detected." (PMID 33924934, 2021). "Single nucleotide polymorphisms (SNPs) in MDM2 and MDM4 have been associated with various cancers." (PMID 33669778, 2021). "The first intron of the MDM2 human oncogene contains the inducible promoter P2, which allows faster processing of transcripts with respect to the constitutive promoter P1 and thus is the mainly responsible for MDM2 overexpression in different types of cancer." (PMID 33410915, 2021). "Finally, a single study analyzed the molecular profiles of 102 878 diverse cancer types and found that MDM2 amplification occurred in 3.5% of the patients." (PMID 33314633, 2021). "Sirt6 also influences MDM2 to suppress Sirt1 activity, thereby also promoting cancer cell death." (PMID 33727672, 2021). "There is a need for dual inhibitors of MDM2/MDMX as it is highly expressed in some cancers." (PMID 34203106, 2021). "Additionally, DDX27, MDM2, RNF40, MMS22L, CCNK and LRP1B were detected as missense mutational cancer gene." (PMID 34313788, 2021). "Genetic studies demonstrate that mutation of MDM2 (C305F), impairing the ribosomal stress signaling and mutation of MDMX (3SA), impairing the DNA damage signaling, can lead to defects of lipid and glucose metabolisms in cancer cells." (PMID 32947864, 2020). "Considering the complexity of interactions between MDM2 and its partners in cancer cells, there are ongoing efforts in our lab to further understand the mechanisms of action for MDM2 inhibitors, such as SP141, focusing on the inflammation and oncogene pathways." (PMID 32397368, 2020). "Thus far, it has not been demonstrated that TSG101 levels are dependent on the functionality of MDM2 in cancers that are driven by this bona fide oncogene." (PMID 32075127, 2020). "It is most likely SP141 is a target-specific anticancer agent that may have a broad-spectrum of activity against MDM2-overexpressing cancers/tumors." (PMID 33291373, 2020). "The on/off rate and/or allosteric effects of these different MDM2-targeted drug leads might impact on MDM2-protein-protein interactions in normal cells and cancer cells." (PMID 32874188, 2020). "Several MDM2 spliced variants have been found in different cancer types which are absent in normal tissues." (PMID 32477121, 2020). "Both NFAT isoforms and MDM2 are activated and overexpressed in several cancer subtypes." (PMID 32397368, 2020).
cancer (continued). "Moreover, Mdm2 is upregulated in multiple cancers such as colorectal cancer, cutaneous melanoma and breast cancer." (PMID 33643919, 2020). "In this review, we summarize the potential oncogenic roles of MDM2 and NFAT1 in cancer cells and discuss the efforts of discovery and the development of several newly identified MDM2 and NFAT1 inhibitors, focusing on their potent in vitro and in vivo anticancer activities." (PMID 32397368, 2020). "Next, MDM2 is overactivated in cancers because of the inhibition of p14ARF tumor suppressor." (PMID 32971841, 2020). "MDM2 is often involved in auto-degradation and proteasomal degradation inside cancer cells." (PMID 32489456, 2020). "Recently, several RPs, including RPL5, RPL11, and RPS14, have been found to associate with TAp73, but not ΔNp73, to overcome MDM2-mediated inactivation, leading to TAp73-induced cancer cell apoptosis." (PMID 32198344, 2020). "In fact, the MDM2 protein is overexpressed in about 10% of human cancers." (PMID 32854179, 2020). "In conclusion, MDM2 amplification is related to resistance to multiple cancer therapeutics and may serve as the novel biomarker and treatment target in the future." (PMID 32611363, 2020).
cancer (continued). "Comparing trajectories for PTEN-cancer cells for monotherapy with these for combination therapy we may notice that Mdm2 inhibitor administration leads to an increase of p53killer oscillation amplitude." (PMID 32724100, 2020). "Overexpression or amplification of MDM2 occurs in a variety of cancer types." (PMID 33679868, 2020). "Therefore, our findings provide evidence and a rationale for targeting MDM2 using small-molecule MDM2 antagonist treatment in combination with ICI therapy to overcome drug resistance or address HPD in cancer immunotherapy clinical studies." (PMID 32655895, 2020). "Blocking MDM2 has anti-inflammatory and anti-cancer effects 54-56." (PMID 33173438, 2020). "Moreover, MDM2 is the therapeutic target with the highest number of substances in clinical trials against various types of cancer in humans." (PMID 32326087, 2020). "For this reason, MDM2 is an effective target in many cancer therapies." (PMID 32425780, 2020). "In addition, therapeutic peptide PMI specifically target MDM2, who just overexpressed in cancer cells, further guaranteeing the safety of PMI-Au SNH." (PMID 32754260, 2020). "MDM2 is often overexpressed in some human and mouse malignant tumors." (PMID 32532965, 2020). "Of note, radiotherapy alone may induce apoptosis in normal cells (that is, in cells with the nominal expression of PTEN and Wip1), while combination therapies using an Mdm2 inhibitor may also induce apoptosis of cancer cells." (PMID 32724100, 2020). "Since MDM2 gene amplification and protein overexpression are found widely in human cancers, investigating the MDM2 related regulatory network under DNA damage is essential to understand its biological function as an oncogene and to identify novel targets for cancer therapy." (PMID 32477121, 2020).